KLF4 (KLF transcription factor 4)
Diseases named in the same sentence as KLF4 in open-access papers (continued):
Sharing a sentence is not in itself a finding about the gene and the disease.
meningioma (continued). "KLF4 K409Q mutations were exclusively found in the presence of TRAF7 mutations and are commonly associated with secretory meningiomas." (PMID 31470906, 2019). "These mutations are present in ~5.5% of grade I meningiomas, and are mutually exclusive with TRAF7, KLF4, and AKT1 mutations." (PMID 31970090, 2019). "Next, we focused on the most common genetic alterations reported so far in meningiomas, including the NF2, SMARCB1, as well as TRAF7, AKT1, SMO, KLF4, PIK3CA, and TERT in non-NF2 mutated meningiomas." (PMID 31470906, 2019). "Known mutations in genes including AKT1, TRRAF7, KLF4, and CDKN2A predispose to meningioma, including high grade meningiomas in the human WHO grading scheme." (PMID 31788444, 2019). "Recently, alterations in other oncogenic genes such as TRAF7, AKT1, KLF4, PIK3CA, SMO, and DMD have also been implicated in meningioma etiology." (PMID 31191822, 2019). "Best known for its role in pluripotency, Klf4 is thought to act as a tumor suppressor in meningioma, being robustly expressed in low grade tumors and downregulated in anaplastic tumors." (PMID 31970090, 2019). "In meningioma, TRAF7 mutations can co-occur K409Q mutation in KLF4, a transcription factor known for its role in inducing pluripotency, and are mutually exclusive with NF2 mutations, chromosome 22 loss, and SMO mutations and was less common in HGMs." (PMID 30082628, 2018). "NF2 mutant meningiomas are in all grades including WHO grade II and III whereas SMO, TRAF7, TRAF7/AKT1 and KLF4 meningiomas tend to be WHO grade I." (PMID 30082628, 2018). "We calculated the significance of association of the driver mutations (NF2, SMARCB1, TRAF7/PI3K, TRAF7/KLF4, POLR2A, Hedgehog) with atypical meningiomas." (PMID 28195122, 2017). "Meningiomas with these alterations carry a significantly higher risk of being atypical as compared with non-NF2 meningiomas, including TRAF7 (with PI3K or KLF4 alterations), Hedgehog or POLR2A mutant tumours." (PMID 28195122, 2017). "To date, the most common alterations in sporadic meningiomas are NF2 mutations or loss of 22q, with non-NF2 mutant meningiomas harboring mutations in in AKT1, TRAF7, KLF4, POLR2A and SMO16–18." (PMID 28775249, 2017). "We also performed Sanger sequencing to check for the presence of mutations previously reported in meningioma driver genes, including regions of NF2, AKT1, TRAF7, KLF4, SMO, and the TERT promoter." (PMID 28552950, 2017). "Next-generation sequencing has characterized recurrent somatic mutations in NF2, TRAF7, KLF4, AKT1, SMO, and PIK3CA, which are collectively present in ~80% of sporadic meningiomas." (PMID 27458586, 2016). "The KLF4 gene located on chromosome 9q, is encoding 3 C2H2 zinc finger motifs and has been shown to be mutated in 10% of meningiomas." (PMID 27429002, 2016). "PIK3CA co-mutations are also found in meningiomas with TRAF7 mutations but without KLF4 mutations, and PIK3CA is also associated with activation of mTOR signaling, as with AKT1 alterations." (PMID 41372821, 2025). "A significant interaction between TRAF7 and KLF4 was observed in meningioma." (PMID 40181456, 2025). "In summary, mTOR pathway activation via AKT1 or PIK3CA mutations promotes cell proliferation and acts together with TRAF7 dysfunction in meningiomas without KLF4 co-mutations." (PMID 41372821, 2025). "Interestingly, meningiomas with mutations in TRAF7, KLF4, AKT1 and SMO, as well as POLR2A, were later described by Nassiri and colleagues to have a more favorable patient prognosis compared to other genetic driver mutations." (PMID 39273576, 2024). "Furthermore, KLF4-K409Q-expressing meningioma cells show high levels of PI3K-AKT-mTOR pathway activation and respond to mTOR inhibitors." (PMID 38571886, 2024).
meningioma (continued). "The most common genetic aberration in meningiomas is functional loss of NF2 and occurs in both low- and high-grade meningiomas, whereas NF2-wildtype meningiomas are enriched for recurrent mutations in TRAF7, KLF4, AKT1, PI3KCA, and SMO and are more frequently benign." (PMID 38571886, 2024). "Meningiomas in the first group are devoid of NF2 alterations and chromosomal instability; may feature AKT1, TRAF7, or KLF4 mutations; have the best prognosis; and are expected to respond to cytotoxic drugs." (PMID 37296907, 2023). "CNVs deleting NF2 on chromosome 22q are early events underlying Immune-enriched or Hypermitotic meningioma tumorigenesis, but Merlin-intact meningiomas encode SSVs targeting TRAF7, AKT1, or KLF4 that may be tumor-initiating." (PMID 36993679, 2023). "Furthermore, several disease-causing mutations, including NF2, TRAF7, KLF4, AKT1 and SMO, have been described in meningiomas and compounds specific for driver mutations are currently under investigation in clinical trials." (PMID 38102708, 2023). "Indeed, KLF4 meningiomas share a unique secretory phenotype, characterized by glandular lumina with secretory globules, and tend to cause disproportional peritumoral edema." (PMID 36937440, 2023). "Group 1 meningiomas have the best prognosis, are free of NF2 mutations and chromosomal instability, may include AKT1, TRAF7, or KLF4 mutations, and are predicted good responses to cytotoxic therapies." (PMID 38001599, 2023). "Indeed, missense mutations in TRAF7, KLF4, and AKT1 exist in 30%, 14%, and 12% of non-NF2 meningiomas, respectively." (PMID 38001599, 2023). "In addition, KLF4 meningiomas had high expression of carcinoembryonic antigen family members CEACAM6 and CEACAM5." (PMID 36937440, 2023). "On the other hand, there are no reports of meningiomas with only AKT1 or KLF4 mutations, suggesting that a missense TRAF7 alteration is pre-requisite for AKT1 or KLF4 mutations to cause tumor." (PMID 36937440, 2023). "Interestingly, AKT1 and KLF4 meningiomas expressed genes specific for PI3K/AKT signaling pathway, suggesting overlapping gene signatures between the two subtypes." (PMID 36937440, 2023). "Merlin-intact meningiomas can encode somatic short variants (SSVs) targeting TRAF7, PIK3CA, AKT1, KLF4, or the Hedgehog pathway, but some of these variants may be passenger mutations that do not influence meningioma tumorigenesis." (PMID 36993679, 2023). "Both TRAF7 and KLF4 alterations in meningioma are loss-of-function mutations and therefore not directly targetable." (PMID 36181606, 2023). "In addition, both AKT1 and KLF4 meningiomas demonstrated trending enrichment of the “PI3K/AKT signaling pathway”." (PMID 36937440, 2023). "A frequent aberration that can co-occur with TRAF7 is KLF4 mutations in up to 50% of NF2-nonmutated meningiomas of grade 1." (PMID 35565385, 2022). "The combination is intriguing: AKT1/TRAF7 mutations are associated with meningothelial histology and basal localization, while KLF4/TRAF7 mutations are highly specific for secretory meningioma without any predominant localization." (PMID 35984495, 2022). "Mutations in SMARCE1, BAP1, KLF4/TRAF7, TERT promoter, and CDKN2A/B deletion, H3K27me3 loss and methylation profiling are now officially associated with the classification and grading of meningiomas." (PMID 34846640, 2022). "Irrespective of the histological grade, most meningiomas (55%) exhibit NF2 alterations, while NF2 wild-type meningiomas may harbor mutations in TRAF7, KLF4, PIK3CA or SMO." (PMID 35049691, 2022).
meningioma (continued). "The analyses here were initiated after diagnostic work-up of the tumors of a 47-year-old male patient with two independent meningiomas having identical somatic TRAF7 mutation N520S, but separate AKT1 (skull base, meningothelial) and KLF4 (convexity, secretory type) hotspot mutation." (PMID 35984495, 2022). "In line with previous publications, we could validate the overlap of certain meningioma relevant mutations such as AKT1 and KLF4 with TRAF7 mutations." (PMID 35213082, 2022). "Furthermore, KLF4 and TRAF7 seem to be associated with secretory meningiomas with more aggressive behavior due to increased swelling of the brain." (PMID 34679551, 2021). "Found in over 50% of non-NF-2 tumors, TRAF7 mutations independently induce meningioma growth, but more commonly act in combination with one of several co-mutations including KLF4, and ATK1." (PMID 34638590, 2021). "In addition to tumor location, KLF4/TRAF7 mutations are independently correlated with secretory histopathology, with nearly all secretory meningiomas harboring this combination of mutations." (PMID 34638590, 2021). "KLF4 mutations are present in ~50% of non NF2 mutated tumors and in up to 9–12% of all meningiomas." (PMID 33801089, 2021). "KLF4 K409Q missense mutations are present in up to 50% of NF2 nonmutated meningiomas, often co-present with TRAF7 mutations, and lead to upregulation of HIF-1a pathway." (PMID 34679551, 2021). "In contrast, we could not find in our WHO grade 1 tumors and control populations, non-synonymous genetic variants, for other genes previously reported to be recurrently mutated in meningiomas such as the TRAF7, AKT1, KLF4, TERT, and PIK3CA genes." (PMID 34868937, 2021). "Tumors with KLF4 mutations are associated with larger peritumoral brain edema, localize to the anterior and middle cranial skull base, and when present with TRAF7 mutations are predictive of a secretory meningioma phenotype." (PMID 33346248, 2020). "Moreover, mutations of NF2 are most frequent in fibroblastic/transitional meningiomas, KLF4 and TRAF7 in secretory meningiomas, and AKT1 mutations in grade I meningothelial meningiomas of the skull base and spine." (PMID 32244473, 2020). "We first searched for known meningioma driver mutations in each sample, defining the distribution of benign versus atypical meningiomas in each of the molecular subgroups including NF2, TRAF7 (co-mutated with PI3K pathway or KLF4), Hedgehog and POLR2A mutant tumours." (PMID 28195122, 2017). "While inactivating mutations in NF2 have been described in 30 to 60% of sporadic meningiomas, recent studies have shown that non-NF2 meningiomas harbor activating mutations in SMO (L412F and W535L), AKT1 (E17K), and KLF4 (K409Q), as well as inactivating mutations of TRAF7." (PMID 25347344, 2014). "However, there are multiple feedback mechanisms that may limit the impact of TRAF7 alterations alone, including those related to KLF4 described in meningioma." (PMID 41372821, 2025). "Among other targets, this leads to the transcriptional activation of fibroblast growth factor 3 (FGF3) expression in KLF4-K409Q-expressing cells, not present in wild-type KLF4-expressing cells, and KLF4-K409Q-mutated meningiomas expressed higher levels of FGF3 compared to KLF4-wild-type tumors." (PMID 38571886, 2024). "In accordance with previous findings, mutations in SMO, KLF4, AKT1, PIK3CA, and TRAF7 were exclusive to the benign methylation class, suggesting that their presence could be used as a surrogate for the methylation profile to identify benign meningiomas." (PMID 37296907, 2023). "Among the non-NF2-mutated group, the most common oncogene in WHO grade I meningiomas is TNF receptor-activated factor 7 (TRAF7), located on chromosome 16p13 (mutated in nearly 25% of all meningiomas), followed by the mutation in codon K409Q of KLF4 (encountered in about 15% of benign meningiomas)." (PMID 37760490, 2023).
meningioma (continued). "Importantly, the rest of the tumor samples, including meningiomas harboring only TRAF7 mutation or together with mutations in genes other than KLF4, had no detectable levels of FGF3 mRNA." (PMID 35996584, 2022). "In addition, recent genomic analyses of meningioma using next-generation sequencing have identified mutations in the TNF receptor-associated factor 7 (TRAF7), the Kruppel-like factor 4 (KLF4), the v-Akt murine thymoma viral oncogene homolog 1 (AKT1), and the smoothened (SMO) gene." (PMID 32742192, 2020). "In addition to the established association of meningioma with pathogenic aberrations in the tumour suppressor gene NF2, genomic analyses have identified genes including TRAF7, KLF4, AKT1, SMO, PIK3CA and POLR2A to possess recurrent mutations in low grade non-NF2 mutant meningioma." (PMID 33167358, 2020). "However, mutations in TRAF7 can be present in isolation, though often they can co-occur with KLF4, AKT1, or PIK3CA mutations, whereas mutations in SMO and POLR2A are usually mutually exclusive Interestingly, the meningiomas arising from SMO and AKT1-MTOR aberrations often arise in the skull base." (PMID 33194703, 2020). "Similarly, TRAF7 and KLF4 mutations have been linked to meningioma, but were not assessed by the panel of the present study." (PMID 31191822, 2019). "Notably, TRAF7/KLF4 mutant meningiomas are the secretory subtype." (PMID 30082628, 2018). "Additionally, AKT1 is co-mutated in TRAF7-mutated meningiomas without KLF4 mutations." (PMID 41372821, 2025). "Previous investigations have identified Wnt pathway activation across meningiomas with SSVs targeting TRAF7, KLF4, PIK3CA, POLR2A, the Hedgehog pathway, and even NF2 and SMARCB125." (PMID 39251601, 2024). "Other genetic alterations, exclusive of NF2 that are reported in sporadic adult meningiomas, include TRAF7, SMO, KLF4, AKT1 and PIK3CA." (PMID 39612013, 2024). "Molecular differences in meningiomas have different demographic characteristics, with NF2-mutant meningiomas being more common in males, while KLF4- and POLR2A-mutant meningiomas are more common in females." (PMID 39796693, 2024). "AKT1 meningiomas displayed high relative levels of HTRA1 and transferrin genes relative to KLF4 tumors, while KLF4 tumors overexpressed CEACAM6, DEGS2, and TSPAN12 relative to AKT1 tumors." (PMID 36937440, 2023). "A recent study of 469 meningiomas suggested a 22x higher recurrence rate in aggressive subgroups (NF2, PI3K, HH, TRAF7) compared to others (KLF4, POLR2A, SMARCB1)." (PMID 35213082, 2022). "Molecular analysis revealed that there were 152 NF2 meningiomas (54.1%) and non-NF2 meningiomas: 45.9% (129 cases) including “AKT1”: 11.4% (32 cases), “KLF4”:5.7% (16 cases), “POLR2A”:16 cases (5.7%), “SMO”: 0.7% (2 cases), and others:22.1% (62 cases)." (PMID 35570314, 2022). "Low-grade meningiomas can also present other genetic alterations, particularly affecting SMO, TRAF7, KLF4 AKT1 and PI3KCA." (PMID 34679551, 2021). "Meningothelial and transitional meningiomas are more frequently seen in SMO, TRAF7/AKT1, and TRAF7/KLF4 mutant tumors." (PMID 30082628, 2018). "Furthermore, several typical meningioma locations have distinct related genomic markers (e.g., anterior skull base: SMO, AKT1E17K, TRAF7; central skull base: AKT1, KLF4, TRAF7, POLR2A, Convexity: NF-2, LOH chromosome 22, BAP1)." (PMID 38017560, 2023). "Mutations in Krüppel-like factor 4 (KLF4), a transcription factor in oncogenic activation, have been detected in about 50% of NF2-nonmutated meningiomas." (PMID 37760490, 2023). "In our studies, no meningiomas had detectable levels of FGF3 mRNA, except for tumors carrying mutations in TRAF7 and KLF4." (PMID 35996584, 2022). "Out of all identified DEGs upregulated by either WT or mutant KLF4, only 36 genes were found to be shared among the cell lines; we inferred that some KLF4K409Q-dependent genes may also be upregulated in meningioma cells and promote tumor growth." (PMID 35996584, 2022).
meningioma (continued). "Without exception, all meningioma samples express high levels of KLF4 mRNA isoform 2, varying from 0.1 to 4.4 copies per one copy of GAPDH mRNA." (PMID 35996584, 2022). "Thus, the roles of both mutant KLF4 and TRAF7 in growth and the secretory clinical manifestation of meningiomas also merit further analyses." (PMID 35996584, 2022). "Unfortunately, the effect of Simvastatin (a medication in Statins class) did not translate into our KLF4 meningioma model." (PMID 32245394, 2020). "Genomic sequencing was also performed and mutations in NF2, TRAF7, SMO, KLF4, and AKT1 did not predict RB1 S780 staining or progression in grade 1.5 meningiomas." (PMID 33346248, 2020). "While KLF4 or AKT1 mutations almost always co-occurred with TRAF7 mutations, they did not occur together; SMO-mutated meningiomas all harbored the activating L412F mutation." (PMID 31652973, 2019). "NF2 mutations were found in 44% of the cases, while common genetic alterations in meningiomas of other locations (TRAF7, AKT1, SMO, KLF4, PIK3CA, and TERT) were lacking in non-NF2-associated cases." (PMID 31470906, 2019). "A recent immunohistochemical survey in GI meningiomas identified a number of SC markers, including OCT4, NANOG, SOX2, KLF4, and c-MYC, on microvessels that led to the suggestion that these vessels may be associated with meningioma initiation." (PMID 31083655, 2019). "Although the role of KLF4 in the differentiation of meningioma is not known, it would be intriguing to explore if it controls the transcription of NHERF1, ERMs or other proteins involved in epithelial polarity." (PMID 29983887, 2018). "Thus, according to this study, five different molecular subgroups of meningiomas: NF2/SMARCAB1, KLF4/TRAF7, PI3K/TRAF7, Hedgehog, and POLR2A." (PMID 30279357, 2018). "POLR2A-mutant meningiomas do not exhibit mutations in other meningeal driver genes, such as NFE2, TRAF7, KLF4, AKT1, or SMO." (PMID 30279357, 2018). "Additionally, alterations in other genes such as SMO, AKT1, TRAF7, and KLF4 have been identified, particularly in non-NF2 mutant meningiomas, indicating a heterogeneous molecular landscape that may influence both prognosis and treatment response." (PMID 41007735, 2025). "A combination of KLF4 and TRAF7 genetic mutations, characteristic of secretory meningiomas, has been identified, with KLF4 mutations being unique to this type and not observed in other meningioma variants, indicating high specificity." (PMID 38975554, 2024). "Interestingly, none of the other meningioma subtypes with characteristic alterations, e.g. mutations in NF2, TRAF7/KLF4 or BAP1, or YAP1 fusion, seem to form epigenetic clusters that are distinct to the same extent." (PMID 33319313, 2021). "Due to lack of secretory meningiomas and TRAF7 mutations in our cohort, the absence of KLF4 K409Q in our cohort may be expected." (PMID 31470906, 2019). "Interestingly, this meningioma subtype was significantly correlated with a lack of NF2 mutations, which suggests that novel mutations in KLF4 and TRAF7 may both be mutually exclusive to alterations in NF2111." (PMID 38879686, 2024). "Moreover, TRAF7 meningiomas express >5-fold higher levels of VEGFA compared to NF2 tumors, suggesting that VEGFA together with other DEGs from the RAP1 signaling pathway may be responsible for the secretory phenotype of KLF4 meningiomas." (PMID 36937440, 2023). "At the time of sequencing, our clinically validated targeted NGS panel did not include several well-known meningioma driver genes (TRAF7, KLF4, or POLR2A), which is a limitation to this study." (PMID 36845294, 2023). "While NF2 gene inactivation has long been recognized as a key driver of meningioma tumorigenesis, more recent studies have identified non-NF2 alterations, particularly those involving the TRAKLS genes (TRAF7, AKT1, KLF4, SMO), as well as other genetic changes not otherwise classified." (PMID 40951339, 2025).